BECN1 (beclin 1)
Diseases named in the same sentence as BECN1 in open-access papers (continued):
Sharing a sentence is not in itself a finding about the gene and the disease.
cancer (continued). "Frameshift and truncation mutations in UVRAG, an important BECN1 interactor during autophagosome and lysosome fusion, are found in cancer cells and also lead to reduced autophagy and increased tumorigenicity." (PMID 34829881, 2021). "Becn1+/− mice are more susceptible to develop spontaneous or oncogene‐activation‐driven malignancies than their wild‐type counterparts." (PMID 34459017, 2021). "All the evidence regarding Beclin-1 ubiquitination indicates that IL-17B contributes to the regulation of the stemness of cancer cells, but the underlying molecular mechanisms are incompletely understood." (PMID 33649532, 2021). "The role of transduction signaling protein EP300 mutated in cancer has been evidenced that it activated miRNA MIR17 to negatively regulate target genes BECN1 and CD28 to promote cell proliferation and escape the immune checkpoint." (PMID 33802957, 2021). "Loss of the BECN1 gene is observed in numerous cancers including human ovarian, breast, and prostate cancers." (PMID 33802014, 2021). "Beclin-1, a mammalian orthologue of the yeast autophagy-related gene Atg6, induces autophagy to inhibit tumorigenesis and is associated with the development of several cancers." (PMID 34525121, 2021). "Becn1 hyperexpression was positively associated with both overall and progression-free survival rates of the cancer patients (P<0.05)." (PMID 33425768, 2020). "Beclin-1 regulates autophagic activity toward the suppression of tumorigenesis and a decrease in its expression causes cancer proliferation and tumorigenesis." (PMID 33375363, 2020). "Allelic loss of BECN1 was also reported in a variety of cancers, including breast, ovarian and prostate cancers." (PMID 33020404, 2020). "Several signaling transduction pathways of cancer have been implicated in autophagy, such as the Akt/mTOR pathway and the Beclin 1/Bax pathway, and recent studies have reported that ROS are important triggers of autophagy under various circumstances." (PMID 33321911, 2020). "In several cancer‐cell lines and mice models, the loss of BECN1 results in an inhibition of autophagy and an upsurge in cell proliferation." (PMID 32935427, 2020). "It was also reported that loss of Beclin-1 results in failure of autophagy and cancer promotion mediated by accumulation of p62." (PMID 31007847, 2019). "Mutations in gastric (p.N8K, p.R389C) and colorectal (p.P350R) cancers have been reported, and around 0.5% of patients were found to have BECN1 mutations across different cancer types." (PMID 31877888, 2019). "Many studies showed, Beclin 1 dysfunction has been implicated in many disorders, including cancer and neurodegeneration." (PMID 31816601, 2019). "High expression of the autophagy-associated genes, LC3 and Beclin-1, are reportedly associated with a poor prognosis in various cancer patients." (PMID 30627053, 2019). "Within this context, autophagy regulation by Beclin 1 has been shown to play a major role in tumorigenesis in several cancer types, and the molecular mechanisms underlying its effects are being elucidated." (PMID 31877888, 2019). "Modified themes of BECN1 functions in these membrane associated complexes have emerged, which makes it a target for therapeutic intervention in pathologies ranging from cancer to Alzheimer’s disease." (PMID 30370269, 2018). "In mice, monoallelic deletion of haplo-insufficient Becn1, results in autophagy deficiency, leads to spontaneous development of malignant tumors, and stimulates development of hepatitis-B-induced premalignant liver lesions." (PMID 26222012, 2016).
cancer (continued). "We evaluated the association between stromal beclin 1 positivity and Ki-67 LI in carcinoma cells at baseline." (PMID 26984766, 2016). "Beclin 1 and LC3 immunoreactivity in carcinoma cells increased following exemestane treatment, and the stromal beclin 1 at baseline was associated with poor clinical and pathological responses to exemestane in this study." (PMID 26984766, 2016). "In mice, heterozygous mutations of Beclin-1 gene increase cell proliferation and cancer development, but Beclin-1 is expressed in wild type." (PMID 26494988, 2015). "Studies have demonstrated that aberrant expression of Beclin-1 in diverse kinds of cancer is linked with poor prognosis." (PMID 26561802, 2015). "We found that the BECLIN 1-positive cancers associated with the patients deceased during the study were indeed negative for vacuolar LC3 staining and highly expressing BCL-2." (PMID 25136588, 2014). "In fact, cancer was the first human pathology associated with autophagy, as revealed by the discovery that expression of Beclin 1 was down regulated in 40–75% of human breast and ovarian cancers due to monoallelic deletion of the gene." (PMID 23933736, 2013). "Introduction of beclin-1 into a cancer cell line led to autophagy and loss of cell proliferation and in vivo tumorigenicity." (PMID 23563240, 2013). "For example, one of the alleles of the pro-autophagy gene Beclin-1 is commonly deleted in several forms of cancer, including breast, ovarian and prostate, suggesting a tumor suppressor function for the autophagy pathway." (PMID 22697169, 2012). "Alternatively, Beclin 1 May act through miRNA-mediated control of necroptotic mRNAs, as Beclin 1 has been previously linked to post-transcriptional regulation in cancer cells." (PMID 40971030, 2025). "Beclin-1 dysfunction can cause many conditions, including neurodegeneration and cancer." (PMID 41456028, 2025). "Therefore, to determine the direct effects of BECN1-deficient adipocytes on cancer growth, we established immortalized stromal vascular cell (imSVC) lines with conditional Becn1 KO system (ROSA-CreERT2)." (PMID 38744820, 2024). "Data mining of the HNSCC cohort of the cancer genome atlas (TCGA) revealed that high mRNA expression of ATG5 or Beclin-1 (BECN1) is associated with decreased overall survival, indicating a putative association between increased activity of autophagy and decreased overall survival." (PMID 38291202, 2024). "In addition, introductionof an inactivating mutation in BECN1, which codes for Beclin1,and experimental reduction of its expression lead to enhanced cancer cellgrowth." (PMID 37908768, 2023). "In addition to being genetically linked to tumors, BECN1 has established a closer association with cancer by mediating autophagy." (PMID 35832792, 2022). "The correlation between tumorigenesis and autophagy is complex and context-dependent, and the first association between cancer and the autophagy machinery derived from observations in mice deficient for Beclin 1, since Becn1+/− mice spontaneously develop multiple malignancies at a high rate." (PMID 35392170, 2022). "The possible underlying mechanism that controversial role of BECN1 might be dependent on the cancer cell type and heterogeneity of autophagy." (PMID 35012553, 2022). "Cancer cells derived from cisplatin treatment highly express an autophagy-regulating protein, Beclin-1, which facilitates the conversion of microtubule-associated protein 1 light chain 3 (LC3-I) to the phosphatidylethanolamine conjugated form (LC3-II), a marker of autophagosome formation." (PMID 34321115, 2021). "A lower level of Beclin-1 is known to be associated with human cancer progress." (PMID 32466337, 2020).
cancer (continued). "In addition, upstream positive regulators of Beclin-1, such as UV radiation, resistance-associated gene or Bax interacting factor-1 (Bif-1), have been found downregulated in several types of cancers, including colorectal cancer." (PMID 32245178, 2020). "In addition, we also examined the expression of other proteins that are associated with cancer cell apoptosis and autophagy including Foxo1 and Beclin-1." (PMID 31892846, 2020). "Another common mutation in cancers that leads to autophagy dysfunction is Beclin-1." (PMID 32998777, 2020). "Besides, ROS can modulate autophagy by affecting the activity of various transcription factors such as NF-κB, resulting in the expression of autophagy-associated genes (BECN1/ATG6 or SQSTM1/p62) in cancer cells." (PMID 31583051, 2019). "These apparently contradictory phenomena have been detected in several types of cancer, including GC, in which autophagy-related proteins, such as Beclin 1 (BECN1), microtubule-associated protein 1 light chain 3 (MAP1-LC3), and p62/sequestosome 1 (SQSTM1) have an important prognostic value." (PMID 31370155, 2019). "Autophagy is first associated with cancer through the identification of BECN1." (PMID 31272261, 2019). "The point mutation of beclin 1 rarely occurs in common human cancers." (PMID 26910278, 2016). "Therefore, we appreciate that the definitive causal contributions of the XIAP/cIAP1-Beclin 1-autophagy pathway to cancer still will require further studies." (PMID 25669656, 2015). "For example, high expression of Beclin 1, one of the first identified mammalian autophagy proteins, has been observed to be associated with either favourable or inferior prognosis in different types of human cancers." (PMID 25714809, 2015). "Beclin-1 has been well characterized as playing a pivotal role in autophagy, and its dysfunction has been implicated in many disorders, including embryonic development, cancer, and neurodegeneration." (PMID 25877859, 2015). "Beclin 1 defects caused by the overexpression of Bcl-xL may facilitate tumor malignant differentiation, which results in a more aggressive cancer cell phenotype and poor prognosis of hepatocellular carcinoma." (PMID 23420500, 2013). "In agreement, the monoallelic knock-out of Beclin-1 in mice enhances susceptibility to cancer." (PMID 22697169, 2012). "In addition, the ultraviolet radiation resistance–associated gene (UVRAG), necessary for the tumor suppressor function of Beclin 1, is also monoallelically mutated in many human cancers." (PMID 22745748, 2012). "Therefore, we tested whether secretory factors produced by BECN1-deficient adipocytes are sufficient to promote cancer cell growth." (PMID 38744820, 2024). "Furthermore, since AKT inhibition promotes autophagy during cancer cell death, we investigated whether the genes associated with autophagy, including Atg3, Becn1, and Atf4, were upregulated or downregulated using qPCR." (PMID 38732133, 2024). "Therefore, melatonin‐promoted ATG3 and Beclin 1 expression in CD133− cells might be associated with other cancer stem cell subpopulations." (PMID 37307404, 2023). "In conclusion, it is important to consider that different BECN1 variants can compete with the wild-type for binding with the interactors depending on both the microenvironmental stimuli and the genetic context leading to different effects on autophagy and cancer patient prognosis." (PMID 36008963, 2022). "Furthermore, beclin-1-knockout mice exhibit enhanced susceptibility to cancer development." (PMID 32235610, 2020). "Earlier studies on the mechanism underlying the regulation of autophagy in cancer cells showed that the activation of the JNK pathway may be involved in the regulation of Beclin-1 expression, and the latter event could be responsible for the induction of the autophagic response." (PMID 32362899, 2020).
cancer (continued). "Alterations in expression of various key autophagy genes have been reported for different types of cancer, including breast, lung, pancreatic, bladder cancer, and leukemia. one of the common molecular aberrations is the loss of one of the alleles of the essential autophagy gene Beclin‐1." (PMID 30302772, 2019). "Active EGFR (both, under stimulating normal conditions and also in active mutants found in cancer) binds to BECN1 and phosphorylates it at tyrosine residues, promoting its homodimerization and inactivation." (PMID 40754831, 2025). "While the selected genes play established roles in mitophagy, many of them, such as SRC and BECN1, are also involved in other cellular pathways, including autophagy and cancer-related signaling." (PMID 39859167, 2025). "In cancer, autophagy has been shown to be an important anti-cancer mechanism in vivo, as the expression level of beclin-1 (a marker autophagy gene) is inversely correlated with the malignancy of brain tumours and directly correlated with survival." (PMID 41511337, 2025). "The positive correlations between the expression of PINK1, SRC, BECN1, and OPTN and drug sensitivity suggest that higher levels of these genes are associated with increased vulnerability of cancer cells to treatment." (PMID 39859167, 2025). "Previous studies have shown that BECN1 influences ferroptosis through the xCT/GPX4 pathway in various types of cancer cells." (PMID 39940841, 2025). "Here, we illustrate that SRC modulates autophagy through BECN1 phosphorylation, which plays an essential role in aberrant cell proliferation in multiple cancer types." (PMID 40754831, 2025). "Ceramide can trigger autophagic cell death in cancer cells by modulating the activity of autophagy-related proteins such as Beclin-1 and Atg5." (PMID 40226357, 2025). "Melatonin promotes autophagy in cancer cells by regulating key proteins of autophagy (Beclin-1, LC3-II, ATG7, etc.)." (PMID 40756978, 2025). "The downregulation of Beclin-1 hinders autophagy, allowing cancer cells to evade autophagic cell death and facilitating tumor progression." (PMID 40710325, 2025). "Beclin-1 plays a crucial role in linking autophagy and apoptosis in the control of cancer advancement." (PMID 39650649, 2024). "Knockdown of Atg5 or BECN1 in cancer cells infected with bacteria significantly increases bacterial proliferation and slows down cancer cell growth." (PMID 38262996, 2024). "IL-6 has been documented to enhance the chemoresistant properties of several types of cancers, for example through its ability to induce the phosphorylation of BECN1 and to control autophagic activity." (PMID 38440120, 2024). "In contrast, suppression of autophagy promotes cancer cell growth and Beclin-1 heterozygous disruption increases spontaneous tumorigenesis." (PMID 39178313, 2024). "Further investigation is essential to understand Beclin-1’s intricate role in cancer by studying its interactions with pathways such as autophagy." (PMID 39650649, 2024). "Another study showed that integration of CBD into a bionic carbon monoxide nanocomplex (HMPOC@M) increased autophagic flux and promoted cancer cell death through the activation of the class III phosphatidylinositol 3-kinase (PI3K-III)/BECN1 (Beclin-1) complex." (PMID 38731434, 2024). "Strong evidence indicates Beclin-1 plays a critical role in controlling autophagy in various human cancer types and its intricate connection with apoptosis and ferroptosis." (PMID 39650649, 2024). "Understanding how Beclin-1 integrates signals from these pathways can uncover how cancer cells react to stress and treatment evasion." (PMID 39650649, 2024). "Research has revealed that decreased Beclin-1 expression was found in certain cancers like glioblastomas, ovarian, hepatocellular, and oesophageal cancers." (PMID 38596136, 2024). "While its role in cancer is intricate, Beclin-1 is crucial clinically, as its levels can impact how cancer patients respond to chemotherapy." (PMID 39650649, 2024).
cancer (continued). "Knockdown of Beclin-1 has been shown to reverse Bortezomib resistance in cancer cells by inducing apoptotic cell death." (PMID 38412186, 2024). "The relationship between BECN1 and cancer progression has garnered significant interest due to its involvement in membrane nucleation and response to cellular stress." (PMID 38744820, 2024). "Celastrol promotes the suppression of the tumors and triggers autophagy in cells with cancer via modulating signaling networks including Akt/mTOR, Beclin‐1, NF‐κB, ROS, HSP90, MAPK, and the proteasome." (PMID 39436197, 2024). "Cancer cells change metabolism to survive, possibly through Beclin-1 affecting metabolic reprogramming by regulating autophagy, which links to glucose and oxidative stress." (PMID 39650649, 2024). "The Beclin-1 NES mutation hinders its capacity to induce autophagy during food scarcity and to inhibit cancer progression." (PMID 39650649, 2024). "The haploinsufficiency of Beclin 1 (BECN1), autophagy protein, is believed to contribute to cancer pathogenesis and progression." (PMID 38787424, 2024). "The current portion concentrates on Beclin-1-mediated autophagy regulation’s involvement in cancer drug resistance and radioresistance." (PMID 39650649, 2024). "Loss of key autophagy genes, such as Beclin-1 (BECN1), has been associated with increased tumorigenesis in various cancer models." (PMID 39376991, 2024). "Current research studies are limited because they fail to consider the impact of the Beclin-1/autophagy axis on immune interactions and how it affects cancer cells’ reactions to immune checkpoint inhibitors." (PMID 39650649, 2024). "In general, Beclin-1 has a significant impact on regulating autophagy, offering various potentials for medical intervention and altering our understanding of cancer biology." (PMID 39650649, 2024). "Knock-down of the LCN2R in cancer cells was sufficient to attenuate the effect of Becn1 KO adipocytes on cancer growth in-vitro." (PMID 38744820, 2024). "This highlights how dysregulation of Beclin-1 and autophagy genes contributes to the development of human cancers." (PMID 39403142, 2024). "Fully grasping Beclin-1’s involvement in cancer requires exploring its links to cellular pathways for new treatment strategies." (PMID 39650649, 2024). "A reduction in BECN1 expression leads to both cancer growth and tumorigenesis, whereas BECN1 regulates autophagic activity to prevent the growth of tumors." (PMID 39463763, 2024). "Out of 90 cancer cases, 55 showed positive Beclin-1 staining (61.1%) and 52 showed positive Atg5 staining (57.8%)." (PMID 39650649, 2024). "This review will delve into Beclin-1’s vital role in controlling autophagy, its influence on cancer growth, drug resistance, and interactions with cell death mechanisms." (PMID 39650649, 2024). "Even though several autophagy regulators like mTOR, ULK1, and AMPK have been identified, Beclin-1 is considered a crucial controller of autophagy in cancer." (PMID 39650649, 2024). "Further investigations revealed that vacuolar protein sorting 34 (VPS34) is the other target of NEDD4-1 in the autophagy machinery and plays an important role in the NEDD4-1-mediated ubiquitination of Beclin-1 in cancer cells." (PMID 36918822, 2023). "In xCT- and BECN1-overexpressing cancer cells, AMPK phosphorylates BECN1, induces binding to SLC7A11, and promotes ferroptosis by directly blocking xCT activity." (PMID 37842240, 2023). "Ectopic overexpression of BECN1 suppresses the proliferation, survival, and migration of different types of cancer cells." (PMID 37108476, 2023). "As JNK separates Beclin-1, it relieves the inhibitory effect of Bcl-2, which is responsible for dictating macroautophagy in cancer-infected cells." (PMID 37893079, 2023). "The expression level of the autophagy-related protein Beclin-1 is also relevant to cancer differentiation." (PMID 37446120, 2023).